CRP (C-reactive protein)
Diseases named in the same sentence as CRP in open-access papers (continued):
Sharing a sentence is not in itself a finding about the gene and the disease.
kidney disease (continued). "Serum BUN, serum creatinine and CRP concentration were also significantly increased with a significant decrease in the serum in albumin concentration, which suggests the incidence of renal disease due to STZ administration." (PMID 36984840, 2023). "One of the potential mechanisms adding to the relationship between DII and the risk of renal disease is the impact of diet-related chronic inflammation in the upregulation of various pro-inflammatory mediators like TGF-β, TNF-α, IL-6, and CRP." (PMID 36313098, 2022). "C-reactive protein (CRP) is an established marker of systemic inflammation in the general population and patients affected by renal disease." (PMID 36611532, 2022). "Taken together, these data suggest that the proteins ASC, IL-18, uPA, EGF, NGAL, and CRP contribute significantly to the inflammatory response in renal diseases." (PMID 35355862, 2022). "Enrolled individuals were investigated for important confounders of kidney disease, such as previous cardiovascular events, and inflammatory surrogates, such as C-reactive protein levels." (PMID 34917437, 2021). "In patients whose initial oxygen requirement did not exceed nasal cannula, 13% had a poor outcome, but this increased to 43.5% and 70% in patients with elevated CRP ≥ 152.5 μg/mL and kidney disease, respectively." (PMID 34441819, 2021). "Our findings suggest that targeting Smad3 is a promising therapeutic strategy for the treatment of fibrotic kidney disease under high CRP conditions." (PMID 34671208, 2021). "In the Modification of Diet in Renal Disease (MDRD) study and in the Trial to Reduce Cardiovascular Events With Aranesp Therapy (TREAT) higher CRP levels have been independently linked to CVD prevalence in diabetic and non-diabetic kidney disease." (PMID 34422725, 2021). "In the Modification of Diet in Renal Disease (MDRD) study involving stage 3 and 4 CKD patients, high CRP (≥0.3 mg/dL) was an independent predictor of both all-cause mortality and cardiovascular mortality in comparison to low CRP <0.3 mg/dL groups." (PMID 31979104, 2020). "Compared with patients excluded due to prior kidney disease (n = 2,836), the study cohort had higher median eGFR (88.7 vs. 56.7 mL/min/1.73 m2), lower median CRP (4.0 vs. 16.0 mg/L), and lower median suPAR (2.7 vs. 4.5 ng/mL) (all P < 0.001)." (PMID 32596235, 2020). "Patients who developed kidney disease or died were older, had more comorbid conditions, more readmissions, lower eGFR, higher CRP, and higher suPAR at index admission compared with patients who were censored at follow-up." (PMID 32596235, 2020). "On the one hand, and contrary to what would have been suspected based on in vitro data, SLE-prone mice supplemented with CRP and CRP-transgenic mice develop a mild kidney disease." (PMID 33664737, 2020). "Based on the multitude of clinical observations, CRP appears to be not only a marker of chronic inflammation but also a mediator of kidney diseases in basic research." (PMID 29951057, 2018). "We chose CRP for this initial development because it is a strong biomarker of adverse outcomes in both chronic heart and kidney disease." (PMID 28346363, 2017). "Disease activity and duration, cumulative damage, antiphospholipid antibodies, high sensitivity C-reactive protein, and renal disease are the most consistent disease-related factors." (PMID 28523037, 2017). "We chose CRP for this initial development because it is a strong biomarker of prognosis in chronic heart and kidney disease." (PMID 28346363, 2017). "Several studies have shown that allopurinol treatment decreases C-reactive protein (CRP) levels, slows the progression of renal disease, decreases the number of hospitalizations, and reduces cardiovascular risk." (PMID 28698529, 2017). "Anti-CRP-Ab were only detected in patients with active renal disease and their levels correlated with SLEDAI (rs = 0.165, p = 0.002)." (PMID 26704903, 2015).
kidney disease (continued). "When controlling for age, sex, eGFR and underlying renal disease the main predictors of increased BAP and TRAP5b levels were low CRP and high iPTH levels." (PMID 25659076, 2015). "The establishment of the NTN model allowed further analysis of the mechanism of CRP suppression of renal disease." (PMID 24167754, 2013). "Two additional papers showed that CRP given as a single injection of 200 μg per mouse had a rapid and long-lasting protective effect on renal disease in both NZB/W and MRL/lpr mice." (PMID 24167754, 2013). "Previous studies have shown that reducing IL-6 and CRP levels may help mitigate inflammatory responses and improve disease outcomes in kidney diseases." (PMID 40717986, 2025). "While increased baseline levels of TGF-β1 have been positively linked to CRP in kidney disease patients, no previous studies have evaluated the link between CRP and TGF-β1 in a surgical population." (PMID 40428821, 2025). "Moreover, a trend for lower CRP levels was seen in participants with renal diseases when they consumed plant proteins in comparison to those consuming animal proteins (e.g., red meat, eggs)." (PMID 40362763, 2025). "Since serum ferritin and uric acid are both acute phase reactants and can be altered in acute inflammation, caution was exerted to minimize the potential confounder via measurement of C-reactive protein and exclusion of patients with inflammatory, infectious conditions, or liver and kidney diseases." (PMID 39493039, 2024). "However, the relationship between CRP and the progression of renal disease in IgAV patients remains controversial." (PMID 37753071, 2023). "Our results revealed significant differences in the CRP values in renal diseases and in gender." (PMID 37626700, 2023). "Because anti-CRP-Ab positivity was observed exclusively in patients with active renal disease, it appears that anti-CRP-Ab could serve as a useful marker of active LN." (PMID 26704903, 2015). "CRP is a short pentraxin and an established biomarker of inflammation in kidney disease." (PMID 24188108, 2013). "In addition to its relation to the progression of renal disease, CRP has been a strong predictor of cardiovascular events in those with reduced renal function." (PMID 20078870, 2010). "We examined the cross-sectional relation of log transformed C-reactive protein (CRP) to renal function (eGFR by Modification of Diet and Renal Disease equation) in African American participants of the community-based Jackson Heart Study's first examination (2000 to 2004)." (PMID 20078870, 2010). "Therefore, we speculate that from the genetic polymorphism of CFH Y402H, reduced binding of C-reactive protein to the CFH protein limits the function of CFH, which results in the development of AMD and kidney disease." (PMID 36604459, 2023). "However, the significant association between cystatin C and C-reactive protein (a marker for inflammation) does not imply a causal relationship, as inflammation plays an important role in the early stages of kidney diseases." (PMID 37663661, 2023). "For renal disease, despite the fact that the exact mechanism has not been identified yet, the mutual inflammatory cytokines (CRP, IL-1, IL-6 and TNF-α) can invade renal tissue causing interstitial fibrosis, tubular injury and infiltration of different inflammatory cells." (PMID 37957565, 2023). "In addition to CRP, copeptin and apelin have been reported as biomarkers of kidney disease." (PMID 36551927, 2022). "Moreover, CRP could markedly mediate tissue fibrosis in several cardiovascular and kidney diseases by activating the TGF-β/Smad3 pathway." (PMID 29951057, 2018). "In accordance with this hypothesis, CRP was significantly associated with hyperfiltration, which is generally reflected by proteinuria among non-diabetic patients with kidney disease." (PMID 27537204, 2016).
kidney disease (continued). "Besides, on the basis of the documented correlation of eGFR to CRP in patients with CKD, increased hs-CRP levels in our ADPKD patients with preserved renal function seems to indicate the likelihood of both CRP mediated inflammatory changes to occur at much earlier stages of renal disease." (PMID 27026905, 2016). "Given the disproportionate burden of renal dysfunction in the African American community, future investigations should focus on the relation of CRP to the development and progression of renal disease and whether lower CRP in longitudinal studies predict improvement in renal function over time." (PMID 20078870, 2010). "Regarding CKD, it has been shown that immunological and inflammatory salivary components, such as IgA, IgG, nitric oxide (NO), and C-reactive protein (CRP), are altered in patients with kidney disease undergoing hemodialysis compared to the healthy group." (PMID 39895822, 2024). "Kidney disease represents a state of chronic inflammation arising from an increase in proinflammatory mediators, such as TNF-α, CRP, and interleukin-6." (PMID 37096248, 2023). "Age, kidney disease, creatinine (CREA), lactate-dehydrogenase (LD), C-reactive-protein (CRP) and lymphocyte (LYM) concentration showed the strongest independent associations with the risk of death in the multivariate regression analysis." (PMID 35210926, 2022). "The ULSAM cohort study, conducted in Sweden with 1110 men aged 70 to 71 years, also indicates that CRP and IL-6 levels decreased with higher dietary fibre intake and that lower fibre intake was more strongly associated with mortality in the elderly with kidney disease than in those without it." (PMID 36297103, 2022). "In the final multivariate model age, kidney disease and CREA, and LD, CRP and LYM concentrations showed the strongest independent associations with the risk of death." (PMID 35210926, 2022). "TNF-α: tumor necrosis factor alpha; IL-6: interleukin 6; CRP: ultra-sensitive C-reactive protein; Hcy: homocysteine; KDQOL-SF 36: kidney disease quality of life short form 36 questionnaire." (PMID 29694512, 2018). "Clinically, serum levels of CRP are increased in patients with AKI, but there have been very few studies addressing the role of CRP in kidney disease." (PMID 28886014, 2017). "More recently, analyzing data from the National Health and Nutrition Examination Survey III demonstrated that high fiber intake was inversely related to C-reactive protein (CRP) levels and mortality in subjects with kidney disease." (PMID 28589039, 2017). "In multivariable analysis (accuracy UC = 0.93), older age, cardiovascular and kidney diseases, FPG ≥ 126 mg/dl, C-reactive protein, and P/F ratio, but not previous DM, were independent risk indicators." (PMID 40314776, 2025). "Patients with kidney diseases often exhibit a microinflammatory state, characterized by elevated levels of interleukin-6 (IL-6), tumor necrosis factor-alpha (TNF-α), and C-reactive protein (CRP)." (PMID 41356816, 2025). "A study has indicated higher CRP levels in IgAV patients with renal impairment than those without renal disease." (PMID 37753071, 2023). "Renal function as measured by Modification of Diet in Renal Disease (MDRD) value were not significantly correlated with CRP levels." (PMID 31788733, 2019). "Anti-CRP-Ab positivity was exclusively observed in patients with active LN 15/46 (33 %), while it did not occur in patients with inactive renal disease (0/11, p = 0.051)." (PMID 26704903, 2015). "C-reactive protein has been found to be a good biomarker of cardiovascular events and mortality both in the patient with and without renal disease." (PMID 22564753, 2012). "Similarly, the mean serum CRP levels were notably higher in patients than in healthy individuals, indicating a significant relationship between increased CRP levels and the incidence of HF in those without a history of kidney disease (P value < 0.001)." (PMID 40862100, 2025).
kidney disease (continued). "Similarly, the number of comorbidities and C-reactive protein (CRP) showed negative correlations with the Symptoms/Problems of Kidney Disease subscale (p=0.002 and p=0.016, respectively)." (PMID 39328658, 2024). "In such cases of severe kidney disease, CRP and ferritin usually do not increase in such a high magnitude and could have values corresponding with group 3a, and CRP can even in some cases be in the normal reference values." (PMID 29925385, 2018). "TRAEs significantly correlated with the absence of peritoneal metastasis; C-reactive protein level < 1; prior G/GEJ cancer surgery; and past or concomitant pulmonary, thyroid, or renal disease (each p < 0.05)." (PMID 34581902, 2022). "We observed that even though a significant correlation was found between HMGB1 and CRP levels at presentation, only AAV patients without active renal disease had significantly higher serum HMGB1 levels than HC." (PMID 24007972, 2013).
metabolic disorders (206 papers, 2010 to 2026). "High-sensitivity C-reactive protein (hs-CRP) is a known inflammatory biomarker linked to various metabolic disorders." (PMID 40938077, 2025). "Chronic inflammation is a major cause of metabolic diseases, and olive oil’s phenolic compounds have been shown to have potent anti-inflammatory effects by lowering CRP, TNF-α, and IL-6 levels." (PMID 40136590, 2025). "The reduction of the risk of cardio metabolic disorders observed in these patients is also due to the normal glycaemia caused by the increase in CRP level." (PMID 38504163, 2024). "Several studies reported that higher levels of circulating CRP and insulin were associated with metabolic disorders." (PMID 35010768, 2022). "Increases in total daily PA and MVPA were associated with lower fasting plasma insulin and CRP as well as heart rate, thus indicating a lower metabolic disease risk." (PMID 34122148, 2021). "In this group, the CRP and leptin levels were especially high indicating a different pathophysiological background, such as systemic inflammation or metabolic disorder, which we believe increases the cardiovascular risk." (PMID 32886313, 2021). "Circulating serum levels of pro-inflammatory mediators, such as interleukin (IL)-1β, IL-6, tumor necrosis factor-α, C-reactive protein, and matrix metalloproteinases, are associated with both PD and lipoprotein disorders in elderly individuals." (PMID 33138320, 2020). "One odd-chain SFA (C17:0) and one even-chain SFA (C16:0) were, respectively, inversely and positively associated with CRP, an inflammatory marker and risk factor of cardio-metabolic diseases." (PMID 29145892, 2017). "Although some authors questioned the causality of the association of CRP with metabolic disorders and related chronic diseases, we found that childhood BMI was associated with elevated level of high-sensitivity CRP in adults." (PMID 25880559, 2015). "Additionally, a cross-sectional study demonstrated an L-shaped association between serum 25(OH)D and CRP in individuals with metabolic diseases, whereas the association was linear in those with pulmonary, gastrointestinal and psychiatric diseases." (PMID 40023976, 2025). "Studies have shown that patients with periimplantitis have elevated levels of inflammatory markers such as C-reactive protein (CRP) and IL-6, which may increase the risk of developing systemic diseases, including cardiovascular and metabolic disorders." (PMID 40217900, 2025). "The inflammatory biomarkers CRP and IL-6 were also significantly greater in the Cd-exposed group than in the control group, with increasing CRP (p < 0.01) and increasing IL-6 (p < 0.0001), indicating that CdCl2 is important in causing inflammation and metabolic disorders." (PMID 39593801, 2024). "In concurrence with metabolic dysfunctions, overfeeding has been well accepted to trigger an inflammatory response, and the release of inflammatory factors such as TNF-α, IL-1β, CRP, and soluble adhesion molecules have also been causally linked to metabolic disorders." (PMID 35126096, 2021). "Minor rs1205 allele (TT) carriers, who showed in our study featuring significantly increased CRP levels, might also be at elevated risk for somatic disorders, especially including cardiovascular and metabolic diseases." (PMID 31788733, 2019). "Doxorubicin exposure increases the production of circulating IL-1-β, IL-6 and C reactive-protein (CRP), enhancing through inflammation, the risk of metabolic diseases and cardiovascular manifestations." (PMID 38935171, 2025). "which demonstrated lower levels of serum CRP in healthy adults and patients with metabolic disorders supplemented with probiotics." (PMID 40735396, 2025). "But studies have shown that CRP has a weak correlation with metabolic diseases and is easily affected by HDL." (PMID 40303640, 2025). "Another commonly studied marker is CRP, a marker of chronic low-grade inflammation and a predictor of cardiovascular and metabolic diseases." (PMID 40805975, 2025).